KCNG3 (potassium voltage-gated channel modifier subfamily G member 3)
Description:
Potassium channel subunit that does not form functional channels by itself. Reduces the deactivation rate. Moderately accelerates activation.
Synonyms: Kv6.3; KV10.1
Tractability: Small molecule: an approved drug acts on it; it belongs to a druggable protein family. Antibody: UniProt places it where antibodies can reach, with high confidence; its Gene Ontology location is reachable by antibodies, with high confidence; UniProt predicts a signal peptide or a membrane-spanning region. PROTAC: ubiquitination databases record sites on it.
Gene: Protein-coding gene on chromosome 2 (42,442,017 to 42,493,982, reverse strand). Ensembl gene ENSG00000171126.
Subcellular location: Cell membrane; Cytoplasm
Subcellular location (Human Protein Atlas): Cytoplasmic bodies
Pathways (Reactome):
Neuronal System: Voltage gated Potassium channels
Gene Ontology:
Molecular function: potassium channel regulator activity; protein binding; monoatomic ion channel activity; voltage-gated potassium channel activity
Biological process: regulation of potassium ion transmembrane transport; regulation of potassium ion transport; action potential; potassium ion transmembrane transport; monoatomic ion transport; potassium ion transport; protein homooligomerization; transmembrane transport
Cellular component: cytoplasm; endoplasmic reticulum; plasma membrane; voltage-gated potassium channel complex; membrane
Genetic constraint (gnomAD): Loss-of-function variants: 15 observed, 24.31 expected, observed/expected ratio (o/e) 0.62, 90% interval 0.41 to 0.95. The synonymous counts are far from expectation, so gnomAD's model fits this gene poorly and the ratio says little. Missense variants: 512 observed, 552.63 expected, observed/expected ratio (o/e) 0.93, 90% interval 0.86 to 1. Synonymous variants: 322 observed, 225.54 expected, observed/expected ratio (o/e) 1.43, 90% interval 1.3 to 1.57.
Homologues: Orthologues: chimpanzee KCNG3 (100% identical), rabbit KCNG3 (98% identical), pig KCNG3 (98% identical), macaque KCNG3 (97% identical), rat Kcng3 (96% identical), mouse Kcng3 (96% identical), guinea pig KCNG3 (91% identical), tropical clawed frog kcng3 (80% identical), dog KCNG3 (79% identical), zebrafish kcng3 (77% identical). Paralogues in human: KCNG2 (41% identical), KCNG1 (41% identical), KCNG4 (40% identical), KCNB2 (37% identical), KCNV1 (32% identical), KCNS1 (31% identical), KCNS3 (31% identical), KCNS2 (30% identical), KCNA1 (30% identical), KCNA7 (30% identical), KCNV2 (30% identical), and 19 more.
Diseases named in the same sentence as KCNG3 in open-access papers:
KCNG3 is named in the same sentence as 5 diseases in open-access papers, as found by Europe PMC text mining. Sharing a sentence is not in itself a finding about the gene and the disease. The quoted sentences say what the papers report.
Abdominal obesity (1 paper, 2019). Excessive fat around the stomach and abdomen. "The top four CpGs that were found to be differentially methylated between individuals with and without abdominal obesity were located at the genes c13orf36, ZC3H12D, MYO9B, and KCNG3 in females; and JPH3, TCP11L1, and GRIK3 in males (one CpG had no annotated gene)." (PMID 31212707, 2019).
epilepsy (1 paper, 2021). A brain disorder characterized by episodes of abnormally increased neuronal discharge resulting in transient episodes of sensory or motor neurological dysfunction, or psychic dysfunction. "Thus, the combined decreased expression of Kcna3 (Kv1.3), Kcnk9 (TASK3), Kcnn3 (SK3), Kcng3 (Kv7.3), and Kcns3 (Kv9.3) around day 8 could lead to increased chances of persistent membrane depolarization, which ultimately may lead to epilepsy." (PMID 34877936, 2021).
Hypertension (1 paper, 2024). The presence of chronic increased pressure in the systemic arterial system. "Kcng3 is a potassium voltage-gated channel that has been suggested to play a role in the depolarization of vascular myocytes and hypertension." (PMID 38173017, 2024).
Obesity (1 paper, 2019). Accumulation of substantial excess body fat. "Nevertheless, the c13orf36 and KCNG3 genes have not already been described in relation to obesity." (PMID 31212707, 2019).
cancer (2 papers, 2009 to 2018). A tumor composed of atypical neoplastic, often pleomorphic cells that invade other tissues. "Several genes that encode these proteins were upregulated in the CD26+ cancer cells: AGR2, BCMP11, CEACAM5/CD66e, CRISP3, KCNG3, KCNH8, LOX and NEO1." (PMID 20021671, 2009).